INS (insulin)
Diseases named in the same sentence as INS in open-access papers (continued):
Sharing a sentence is not in itself a finding about the gene and the disease.
atherosclerosis (continued). "Experimental studies have suggested that insulin may have beneficial as well as potentially harmful effects on the progression of atherosclerosis, as assessed by the expression of proinflammatory mediators and endothelial function." (PMID 24607023, 2014). "Dysfunction of PC 1/3 may induce abnormal release of insulin and GLP-1, thus lead to susceptibility to atherosclerosis." (PMID 24489861, 2014). "Therefore, inhibition of insulin-mediated VSMCs proliferation and migration would be helpful in preventing the development of atherosclerosis and restenosis after angioplasty." (PMID 24888351, 2014). "Insulin may have a deleterious cardiovascular effect by stimulating the sympathetic nervous system involving vasoconstriction and thus promoting atherosclerosis." (PMID 24752580, 2014). "Based on these findings and previous studies, we speculate that the D4 receptor may be a target to inhibit abnormal VSMC growth induced by insulin, which may lead to a novel strategy in the treatment of atherosclerosis." (PMID 24888351, 2014). "The aim of this study is to investigate the effects of sitagliptin on the progression of atherosclerosis in insulin-treated patients with T2DM free of history of CVD, using common carotid IMT, a widely used surrogate marker of atherosclerosis, as the primary endpoint." (PMID 24607023, 2014). "Furthermore, aortic extracts of high-fat insulin-resistant LDL-receptor deficient mice, with lower adiponectin and Irak3 and higher Mcp1, showed accelerated atherosclerosis." (PMID 23620818, 2013). "This may be ascribed to the short follow-up periods of the insulin-treated patients, since atherosclerosis is a long-run process." (PMID 23398881, 2013). "In conclusion, increased CORT exposure in mice with a human like lipoprotein metabolism has beneficial, long-lasting effects on atherosclerosis, despite negatively affecting body fat distribution and insulin sensitivity by promoting fat accumulation in the long term." (PMID 23717502, 2013). "In order to elucidate this relationship, studying the early variation of insulin during induction of hypercholesterolemia may help cognizance the pathogenesis of atherosclerosis." (PMID 23497719, 2012). "PPARγ is a ligand-activated nuclear transcription factor involved in cellular differentiation, cancer, inflammation, insulin sensitization, atherosclerosis, and metabolic diseases, and it has been shown to inhibit NF-κB and to play important roles in several inflammatory processes." (PMID 23199346, 2012). "The likely beneficial effects of the higher expression of PPARA seen here for female liver include increases in HDL levels, decreases in triglycerides via increased beta-oxidation, induction of ABCA1, increases in insulin sensitivity, and protection from atherosclerosis." (PMID 21858147, 2011). "Insulin resistance syndrome is a condition in which there is an impaired response of body cells (muscle, fat, and hepatic) to insulin resulting in impaired endothelial function and enhanced atherosclerosis; which requires higher doses of insulin for normal function." (PMID 22654727, 2011). "Increased levels of glucose, insulin, C-peptide and HbA1c in the cord blood of IDM have been shown to be predictive for the clinical course of the infant as well as susceptibility to atherosclerosis." (PMID 21911328, 2011). "Thus, Egr-1 upregulation, which is frequently observed in atherosclerosis, is likely to be involved in insulin-mediated TRAIL downregulation." (PMID 20634940, 2010). "The insulin-sensitizing drugs TZDs, as PPARγ agonists, have beneficial effects on serum lipids in diabetic patients and have also been shown to inhibit the progression of atherosclerosis in animal models." (PMID 19737384, 2009). "It has also been suggested that the effects of RGZ in foam cell formation and atherosclerosis may differ in the degree of insulin resistance." (PMID 18485218, 2008).
atherosclerosis (continued). "In addition to its importantroles in insulin sensitivity and glucose homeostasis, PPAR-γ is also associated with CVD such as coronaryheart disease, atherosclerosis, and stroke." (PMID 18288291, 2008). "Additionally, PPARs enhance insulin sensitivity during adipocyte differentiation and contribute to the control of inflammation and prevention of metabolic disorders such as atherosclerosis, highlighting their broad physiological importance." (PMID 39983527, 2025). "Existing research indicates that SO may synergistically promote atherosclerosis development through multiple pathways, including hormonal dysregulation, adipo-myokine imbalance, insulin resistance, chronic low-grade inflammation, and lipid metabolic abnormalities." (PMID 41303183, 2025). "In addition to the insulin-independent reduction in high glucose, SGLT2 inhibitors improve risk factors for CVD, such as body weight, systolic blood pressure, uric acid, and lipid profile, and potentially protect against the pathogenesis of atherosclerosis." (PMID 40149704, 2025). "In addition, genetic deletion of MMP12 ameliorates cardiometabolic diseases by reducing circulating lipid levels, obesity-induced low-grade inflammation, WAT dysfunction, insulin sensitivity, and atherosclerosis in a room temperature-housed cardiometabolic mouse model." (PMID 41308745, 2025). "Furthermore, MASLD correlate with impaired vasomotor actions, accelerated atherosclerosis, and coronary artery calcification and may additionally fuel insulin resistance." (PMID 39287794, 2025). "The ability of TZDs to improve insulin sensitivity not only aids in glycemic control but also reduces the metabolic stress placed on the cardiovascular system, which is crucial in preventing the progression of atherosclerosis and other cardiovascular complications." (PMID 39337658, 2024). "Thus, estradiol replacement could have benefits in protection against atherosclerosis and improvement of insulin sensitivity." (PMID 39728272, 2024). "The exact pathogenic mechanisms linking these findings are not yet known, but subtle cortisol autonomy in adrenal adenomas, insulin resistance, and/or abnormal levels of inflammatory adipocytokines may play a pivotal role in the development and progression of atherosclerosis." (PMID 39457527, 2024). "Previous studies have supported that vitamin D may reduce the risk of CVD by blocking the renin-angiotensin system, decreasing the parathyroid hormone levels, reducing inflammation, lowering coagulation, subsequently reducing atherosclerosis, and increasing insulin production." (PMID 39194949, 2024). "A key unanswered question is whether or not insulin resistance at a whole-body level causes atherosclerosis in vivo." (PMID 39401163, 2024). "Furthermore, it has been hypothesized that improving insulin sensitivity will lead to a reduction in cardiovascular events, which ultimately attenuates the progression of atherosclerosis." (PMID 36012362, 2022). "This hypothesis does not refer to the direct relationship between atherosclerosis and improved insulin sensitivity, but rather to the beneficial effects of improved insulin sensitivity on other risk factors in cardiovascular disease." (PMID 36012362, 2022). "Given the vital roles of endothelium-derived nitric oxide and the endothelium in maintenance of vascular tension, platelet adhesiveness and smooth muscle cell proliferation, endothelial dysfunction may contribute to increased risks of atherosclerosis in insulin-resistant individuals." (PMID 35493201, 2022). "Combined treatment with insulin and metformin seems to be particularly beneficial as it reduces the intensity of lipid peroxidation and probably influences the expression of the protein responsible for lipoprotein binding, thus having the potential to inhibit atherosclerosis." (PMID 35742776, 2022).
atherosclerosis (continued). "In addition to modulating insulin sensitivity, resistin plays a role in the development of inflammation and inflammatory diseases (e.g., atherosclerosis and arthritis), regulates carbohydrate and lipid metabolism, and stimulates the proliferation of endothelial cells." (PMID 33924645, 2021). "For example, insulin could lead to the accumulation of lipids in vascular wall with subsequent acceleration of inflammation and extracellular matrix remodeling, which are key features of atherosclerosis development." (PMID 33598483, 2021). "In addition, studies have shown that intermittent hypoxia generates stress that increases the levels of seleno-protein P in human hepatocytes, increasing insulin resistance, accumulating fat in adipose tissue, and aggravating risks of developing atherosclerosis." (PMID 33807959, 2021). "Therefore, the association between insulin treatment and atherosclerosis and its complications in T2DM has not been definitively determined." (PMID 33598483, 2021). "This spectrum of actions suggests that decreased humanin production may be related to the pathophysiology of uremia characterized by insulin insensitivity, activated inflammatory processes, increased oxidative stress, impaired endothelial function, and premature atherosclerosis." (PMID 31385015, 2019). "The specific hypothesis: chloroquine improves insulin sensitivity and decreases atherosclerosis." (PMID 31384309, 2019). "Increased body weight may interact with insulin level and sensitivity by affecting atherosclerosis." (PMID 30470212, 2018). "This may arise through a direct effect from insulin on the pathogenesis of atherosclerosis." (PMID 29590246, 2018). "Therefore, a reduction in SCFA levels in AD mice may lead to the development of atherosclerosis by disturbing lipid metabolism and insulin sensitivity." (PMID 29051579, 2017). "Coordinately regulated by hormones (for example, insulin and glucagon) and nutrients, hepatic lipid metabolism plays a critical role in glucose, lipid and energy homoeostasis, the dysregulation of which leads to fatty liver, insulin resistance and atherosclerosis." (PMID 28327662, 2017). "Thus insulin resistant plays a significant role on mac-complications, especially atherosclerosis." (PMID 29164077, 2017). "Therefore, we hypothesized that insulin induced atherosclerosis and was responsible for the decreased expression of ER-α." (PMID 27832775, 2016). "Our data suggest that insulin promotes the expression of DNA methyltransferases, induces methylation of ER-α second exon region and decreases the expression of ER-α, thereby interfering with estrogen regulation of VSMCs proliferation, resulting in atherosclerosis." (PMID 27832775, 2016). "Elevated levels of total cholesterol, PLTP, RANTES, IL-6, insulin and leptin, which showed correlation with 18F-FMCH uptake, have been linked with increased atherosclerosis thus lending support to the association between 18F-FMCH uptake and the risk of atherosclerosis." (PMID 26852231, 2016). "Insulin-resistant subjects develop more severe and diffuse coronary artery atherosclerosis than insulin-sensitive controls but the mechanisms that mediate this atherosclerosis phenotype are unknown." (PMID 26147990, 2015). "However, there is a possibility that improvement of insulin sensitivity could have indirectly contributed to suppression of atherosclerosis or macrophage form cell formation." (PMID 26606676, 2015). "Because in normal subjects blood concentrations of glucose, lipids and insulin are increased after each meal, and postprandial changes last a long time after the meals, these changes might be of importance in the process of atherosclerosis initiation and development." (PMID 25658240, 2015). "Interestingly, SIRT1 also relies upon AMPK for the regulation of insulin sensitivity and to induce autophagy that is necessary for endothelial cell protection during exposure to oxidized low density lipoproteins that can lead to atherosclerosis." (PMID 26064426, 2015).
atherosclerosis (continued). "However, no distinctive patterns were found between the atherosclerosis-susceptible strains and the resistant strains in fasting glucose, insulin resistance, body weight, islet mass, and fasting lipids." (PMID 25946019, 2015). "However, whether RBP4 is involved in insulin-induced proliferation of VSMCs leading to atherosclerosis remains unclear." (PMID 24604418, 2014). "Growing evidence demonstrates that GA, in conjunction with the GA/HbA1c ratio might be more accurate than HbA1c alone for assessing insulin secretory dysfunction, which resulted in glycemic fluctuation and variability and can be used to predict atherosclerosis." (PMID 24755655, 2014). "Similarly, isolated ApoE deficiency (ApoE−/−), a model of hyperlipidemia and atherosclerosis, does not impair insulin sensitivity." (PMID 26167199, 2014). "The exact molecular relationship between insulin, ED and atherosclerosis is presently unknown." (PMID 23497719, 2012). "However, insulin induces smooth muscle cell proliferation and may lead to the progression of atherosclerosis." (PMID 21978180, 2011). "PPAR-γ agonists, the thiazolidinediones (TZDs), increase insulin sensitivity, lower blood glucose, decrease circulating free fatty acids and triglycerides, lower blood pressure, reduce inflammatory markers, and reduce atherosclerosis in insulin-resistant patients and animal models." (PMID 18288291, 2008). "H19 is downregulated in insulin‐resistant skeletal muscle and its restoration improves insulin signaling; conversely, in vascular cells H19 upregulation has been linked to neointima formation and atherosclerosis, indicating tissue‐dependent effects rather than atherogenesis driven by H19 deficiency." (PMID 41567175, 2026). "Elevated insulin levels overactivate the phosphoinositide 3-kinase/protein kinase B (PI3K-PKB) pathway, enhancing the development or progression of atherosclerosis." (PMID 40149860, 2025). "In obese mice, poor insulin signaling in intraperitoneal macrophages increased CD36 expression and oxidized LDL binding and absorption, accelerating atherosclerosis." (PMID 40141412, 2025). "Chronic inflammation driven by TNF-α and IL-6 further exacerbates insulin resistance and VLDL production, while macrophages in blood vessels convert oxidized LDLs into foam cells, promoting the development of atherosclerosis." (PMID 40507946, 2025). "GO and KEGG pathway enrichment analysis highlighted potential signaling pathways, such as AGE-RAGE, PPAR, insulin resistance, TNF, and lipid and atherosclerosis pathways." (PMID 41304686, 2025). "KEGG enrichment analysis revealed that BHEE’s putative targets were significantly associated with signaling pathways central to lipid metabolism and inflammation, including AGE-RAGE, PPAR, HIF-1, insulin resistance, TNF, and lipid/atherosclerosis pathways." (PMID 41304686, 2025). "In the M + insulin + 7RS14α group, key metabolic pathways included cortisol synthesis and secretion, ECM–receptor interaction, nitrogen metabolism, and lipid and atherosclerosis." (PMID 40565658, 2025). "The identified targets were associated with glycolipid metabolism-related pathways, including lipid and atherosclerosis, the AGE-RAGE signaling pathway in diabetic complications, and the insulin signaling pathway." (PMID 40221773, 2025). "The KEGG pathway analysis of overlapping genes suggested relevant pathways such as lipid and atherosclerosis, PI3K-AKT, insulin signaling, advanced glycation end product (AGE)-RAGE, TNF, and mitogen-activated protein kinase (MAPK)." (PMID 39598338, 2024). "The five key genes related to three pathways included the SNARE interactions in the vesicular transport pathway (SNAP23, VTI1A), the insulin signaling pathway (IRS2, PRKAR1A), and lipid and atherosclerosis (CASP1)." (PMID 38674428, 2024).
atherosclerosis (continued). "Premature insulin treatment in T2DM leads to weight gain and a high C-peptide concentration (indexing endogenous insulin release) may be related to microvascular damage, chemiotaxis of inflammatory cells and smooth muscle cells, and proliferation thus contributing to atherosclerosis." (PMID 37959313, 2023). "Furthermore, a reduction in insulin activity in ischemic myocardium could increase oxygen consumption due to a shift from glucose towards fatty acid metabolism, which would accelerate the progression of atherosclerosis." (PMID 38313836, 2023). "We examined the cross-sectional associations of dietary Glycemic Index (GI), Glycemic Load (GL), Dietary Insulin Index (DII), and Dietary Insulin Load (DIL) with cardiovascular disease (CVD) factors in subjects with atherosclerosis." (PMID 37582773, 2023). "PCR array analysis was performed to elucidate the expression of different genes related to various signaling atherosclerosis transduction in HUVECs after being exposed to the DHA, Insulin, and Pal." (PMID 33602249, 2021). "GTTs were carried out on diet-induced insulin-resistant and Leprdb diabetic mouse models treated with RG54 peptide, and the impact of RG54 peptide on atherosclerosis was evaluated in Apoe−/− mice." (PMID 31069401, 2019). "IPA revealed an interaction network between genes mainly involved in inflammatory, insulin and lipid pathways, and our 1H NMR-identified metabolite markers of atherosclerosis." (PMID 31102408, 2019). "As the study population was rather lean, insulin-sensitive and had lower blood pressure and LDL levels, we can exclude the effect of these confounding factors that can affect the progression of atherosclerosis." (PMID 28178313, 2017). "Myograph analyses show decreased aortic contractile response to phenylephrine and increased aortic response to acetylcholine and insulin in LMDP-treated animals, suggesting that LMDP inhibits atherosclerosis through improving vascular function." (PMID 26859892, 2016). "Thus, although our data are associational and not mechanistic, this paradigm suggests that the increased protein glycation that occurs with feeding a high fat/high NaCl diet may enhance the severity of atherosclerosis development in insulin resistant, hypercholesterolemic pigs." (PMID 26147990, 2015). "The KO displays altered expression of transcripts with roles in the glucose-insulin signaling pathway, ECM composition, vasoregulation, redox homeostasis, inflammation, coagulation, atherosclerosis, and endothelial dysfunction." (PMID 26047815, 2015). "Even when fed chow diets, which have been extensively used for the study of hypercholesterolemia, atherosclerosis, and insulin resistance, WHHL rabbits are characterized by hyperlipidemia and spontaneous atherosclerosis in both aorta and coronary arteries." (PMID 25333893, 2014). "Insulin can promote VSMC proliferation and DNA synthesis, playing an important role in the formation of atherosclerosis." (PMID 24604418, 2014). "As a secondary objective, the impact of impaired insulin sensitivity and history of GDM with increased carotid intima media thickness (IMT) a well established marker of early atherosclerosis should be examined in a subgroup." (PMID 25281032, 2014). "Insulin is a highly potent cell growth factor, which can promote VSMC proliferation and DNA synthesis, and plays an important role in the formation of atherosclerosis." (PMID 24604418, 2014). "Notably, pathways such as metabolic pathways, insulin signaling pathway, HIF-1 signaling pathway, FoxO signaling pathway, and lipid and atherosclerosis pathway, etc., aligned with predictions from network pharmacology." (PMID 40438591, 2025). "Elevated circulating insulin levels can directly affect vascular function and contribute to the pathophysiology of the cardiovascular system, including secondary arterial hypertension (SAH) and atherosclerosis." (PMID 40137469, 2025).